HLTF (helicase like transcription factor)
Description:
Functions as a DNA-dependent ATPase and E3 ubiquitin-protein ligase involved in chromatin regulation and DNA damage tolerance (DDT). Catalyzes 'Lys-63'-linked polyubiquitination of monoubiquitinated PCNA at 'Lys-164' in response to genotoxic stress, promoting error-free postreplication repair via template switching. Acts as an epigenetic regulator by promoting recruitment of DNMT1, thereby ensuring DNA methylation inheritance: specifically binds histone H3 trimethylated at 'Lys-9' (H3K9me3) and mediates histone H3 'Lys-23' polyubiquitination (H3K23ub), a docking site for DNMT1, leading to DNMT1 recruitment and replication-coupled DNA methylation maintenance. Catalyzes formation of H3K23ub in two steps: first mediates monoubiquitination together with UBE2E1 and UBE2D2, and then extends ubiquitin chains via 'Lys-63'-linked ubiquitination together with UBE2N and UBE2V2. Also acts as a chromatin redodeling factor, thereby regulating transcription. Exhibits ATP-dependent double-stranded DNA (dsDNA) translocase activity but lacks classical helicase activity; mediates replication fork reversal by concertedly unwinding and annealing nascent and parental strands, thereby suppressing DNA synthesis and maintaining genomic stability. Contributes to nucleotide excision repair by evicting lesion-containing oligonucleotides using its HIRAN and ATPase domains. Can displace single-stranded DNA from triplex structures through ATP-dependent dsDNA translocation. Also has protein clearing activity at the stalled replication fork, facilitating restart of DNA replication.
Synonyms: SMARCA3; HIP116A; RNF80; SNF2L3; ZBU1; HLTF1; HIP116
Tractability: Small molecule: a structure with a bound ligand is known. PROTAC: UniProt records ubiquitination sites on it; ubiquitination databases record sites on it.
Gene: Protein-coding gene on chromosome 3 (149,030,122 to 149,086,554, reverse strand). Ensembl gene ENSG00000071794.
Subcellular location: Nucleus; Chromosome
Subcellular location (Human Protein Atlas): Nucleoplasm
Pathways (Reactome):
Metabolism of proteins: E3 ubiquitin ligases ubiquitinate target proteins
Gene Ontology:
Molecular function: ATP hydrolysis activity; ATP-dependent chromatin remodeler activity; DNA translocase activity; G-quadruplex unwinding activity; histone H3K23 ubiquitin ligase activity; histone H3K9me2/3 reader activity; protein binding; RNA binding; single-stranded DNA binding; ubiquitin protein ligase activity; ubiquitin protein ligase binding; ATP-dependent activity, acting on DNA; ATP binding; hydrolase activity, acting on acid anhydrides, in phosphorus-containing anhydrides; nucleic acid binding; zinc ion binding
Biological process: chromosomal DNA methylation maintenance following DNA replication; DNA damage response; protein K63-linked ubiquitination; protein localization to chromatin; protein polyubiquitination; replication fork reversal; protein ubiquitination; chromatin remodeling; mRNA transcription by RNA polymerase II; positive regulation of transcription by RNA polymerase II; regulation of neurogenesis
Cellular component: chromatin; chromosome; membrane; nuclear replication fork; nucleoplasm; RNA polymerase II transcription regulator complex; nuclear matrix; plasma membrane; nucleus
Genetic constraint (gnomAD): Loss-of-function variants: 39 observed, 34.38 expected, observed/expected ratio (o/e) 1.13, 90% interval 0.88 to 1.48. The upper end of that interval is the gene's LOEUF score, 1.48, which puts it in group 6 of 6, group 1 being the genes least tolerant of losing a copy. Missense variants: 364 observed, 385.24 expected, observed/expected ratio (o/e) 0.94, 90% interval 0.87 to 1.03. Synonymous variants: 101 observed, 129.37 expected, observed/expected ratio (o/e) 0.78, 90% interval 0.66 to 0.92.
Homologues: Orthologues: chimpanzee HLTF (99% identical), macaque HLTF (98% identical), dog HLTF (94% identical), pig HLTF (94% identical), rabbit HLTF (92% identical), guinea pig HLTF (87% identical), mouse Hltf (84% identical), rat Hltf (83% identical), tropical clawed frog hltf (62% identical), zebrafish hltf (52% identical). Paralogues in human: TTF2 (25% identical), CHD5 (17% identical), CHD4 (16% identical), SHPRH (16% identical), RAD54B (16% identical), SRCAP (16% identical), SMARCA2 (16% identical), SMARCA4 (16% identical), CHD3 (16% identical), CHD7 (16% identical), CHD1 (15% identical), CHD9 (15% identical), and 18 more.
Diseases named in the same sentence as HLTF in open-access papers:
HLTF is named in the same sentence as 74 diseases in open-access papers, as found by Europe PMC text mining. Sharing a sentence is not in itself a finding about the gene and the disease. The quoted sentences say what the papers report.
colorectal cancer (13 papers, 2012 to 2024). A primary or metastatic malignant neoplasm that affects the colon or rectum. "HLTF has been associated with several cancers including colorectal cancer, head and neck cancer, Chronic Myeloid Leukemia." (PMID 39480826, 2024). "TGF-β upregulates HLTF which attenuates migration of colorectal cancer cells by hindering TGF-β/Smad signalling." (PMID 39480826, 2024). "HLTF promoter methylation often occurs in colorectal cancer and gastric cancer, but the incidence of HLTF promoter methylation in HCC is very low." (PMID 36670110, 2023). "Methylation of the HLTF gene in colorectal cancer (CRC) cells occurs more frequently in men than women." (PMID 34010296, 2021). "SMARCA3 (also known as Helicase‐like transcription factor, HLTF) is frequently observed in colorectal cancer (CRC) and is negatively associated with the progression of CRC." (PMID 34315468, 2021). "Our aim in this study was to investigate the expression changes of HLTF and SEPT9 genes in the tissue and peripheral blood of patients with colorectal cancer and ultimately find a specific and non-invasive diagnostic biomarker for this disease." (PMID 33936232, 2021). "The helicase-like transcription factor (HLTF) gene—a tumor suppressor in human colorectal cancer (CRC)—is regulated by alternative splicing and promoter hypermethylation." (PMID 31461471, 2019). "Human helicase-like transcription factor (HLTF)–a tumor suppressor in colorectal cancer–is regulated by AS." (PMID 29975766, 2018). "In conclusion we were able to provide evidence that methylation of HLTF and especially HPP1 detected in serum is strongly correlated with cell death in colorectal cancer using LDH as surrogate marker." (PMID 24708595, 2014). "We earlier reported methylation of HLTF and HPP1 to be independent prognostic markers in metastastatic colorectal cancer." (PMID 24708595, 2014). "A tumor suppressor, HLTF is expressed in tumor cells but not in the tumor microenvironment (TME) in early-stage colorectal cancer (CRC)." (PMID 37682902, 2023).
cervical carcinoma (6 papers, 2013 to 2023). A carcinoma arising from either the exocervical squamous epithelium or the endocervical glandular epithelium. "The DNA damage repair-associated gene Helicase-like-transcription factor (HLTF) was identified as a miR-145 target able to confer radio-resistance in cervical cancer cells by enhancing DNA damage repair." (PMID 33803151, 2021). "Up-regulation of HLTF is associated with tumor progression in hypopharyngeal and cervical cancers was over-expressed in our TKI-resistant CML cases." (PMID 30100996, 2018). "Indeed, we have previously shown that truncated HLTF variants are progressively overexpressed during carcinogenesis (head and neck cancer as well as cervical cancer) and replace the wild-type protein." (PMID 25005870, 2014). "MiR-145 targets HLTF mRNA, and its expression level is negatively correlated with that of HLTF in radiation resistant cervical cancer tissues." (PMID 36670110, 2023). "HLTF contributes to radiation resistance by enhancing the DNA damage repair capacity in cervical cancer, while miR-145 overexpression can enhance the radiosensitivity of cervical cancer cells in vivo and in vitro." (PMID 36670110, 2023). "On the other hand, the human ortholog of the yeast Rad5, HLTF, was reported to be overexpressed in radiation resistant recurrent human cervical carcinoma and a knockdown of HLTF in HeLa cells lead to a decrease in cellular proliferation." (PMID 24130896, 2013). "Thus, FSCN1 negatively regulates four transcription factors (HLTF, HBP1, ZNF664, DDX17) and positively regulates ANGPTL4 (an angiogenic factor) and EPHA2 in both HeLa cells and cervical cancer tissues." (PMID 35178306, 2022). "The results showed that the expression of FSCN1 had a significant negative correlation (P < 0.05) with that of HLTF, HBP1, ZNF664, CTGF, DDX17, and KRT18 in cervical cancer tissues." (PMID 35178306, 2022).
colon cancers (6 papers, 2006 to 2023). "HLTF and SHPRH are regarded as candidate tumor suppressor genes, because loss of function or dysregulation has been linked to cancer development, and HLTF is often epigenetically silenced by promotor hypermethylation in colon cancers (~40%)." (PMID 31973093, 2020). "Our cytogenetic data demonstrating the gross chromosomal abnormalities present in Hltf deficient mouse tumor or in HLTF knockdown HCT116 colon cancer cells strongly support this notion." (PMID 22452792, 2012). "The presence of a CIN phenotype in Hltf knockout or knockdown tumor cells also implicates loss of HLTF function as an additional mechanism to induce CIN phenotypes in human colon cancer." (PMID 22452792, 2012). "In this study, we focused on determining the role of loss of HLTF function in the development of colon cancer." (PMID 22452792, 2012). "All these findings indicate that the genomic instability induced in HLTF deficient colon tumors likely plays an important role in the malignant transformation of these tumors." (PMID 22452792, 2012). "In keeping with this idea, inhibition of HLTF gene expression caused by promoter hypermethylation was recently observed in 30–70% of human colon cancers and human gastric carcinoma." (PMID 16762066, 2006). "Furthermore, similar to human colon cancers with a CIN phenotype, we have also found that Hltf deficient mouse colon tumors or HLTF knockdown human colon cancer cells developed more malignant features, such as invasiveness, as compared to the tumor cells that contain functional HLTF." (PMID 22452792, 2012). "To determine whether loss of HLTF function would also lead to a similar tumor-promoting effect in human colon cancer as we demonstrated in the Hltf -/-/Apcmin/+ mouse model, we applied a lentiviral based shRNA knockdown approach to down-regulate HLTF expression in HCT116 human colon cancer cells." (PMID 22452792, 2012). "Epigenetic silencing of HLTF has been implicated in the malignant transformation of adenomas to carcinomas because the HLTF gene is silenced by hypermethylation in 43% of colon cancers." (PMID 34010296, 2021). "Increased tumor growth and genomic instability was also demonstrated in HCT116 human colon cancer cells in which HLTF expression was significantly decreased." (PMID 22452792, 2012). "HLTF has also been found to be frequently inactivated by promoter hypermethylation in human colon cancers." (PMID 22452792, 2012). "We have also demonstrated that down-regulation of HLTF increased chromosomal abnormalities in human colon cancer cells." (PMID 22452792, 2012). "Epigenetic inactivation of HLTF gene expression by promoter hypermethylation has been reported in more than 40% of human colon cancers." (PMID 22452792, 2012). "The HLTF promoter has been found to be hypermethylated in more than 40% of human colon cancers, suggesting that HLTF is a common target for methylation in this cancer." (PMID 22452792, 2012). "HCT116 cells are one of a few colon cancer cell lines that lack HLTF promoter methylation, and express high levels of HLTF." (PMID 22452792, 2012). "Intriguingly, such an implication was also suggested in human colon cancer where HLTF is inactivated by hypermethylation of its promoter." (PMID 16762066, 2006). "In addition, HLTF methylation was demonstrated to be significantly correlated with poor prognosis in human colon cancer patients." (PMID 22452792, 2012). "We then performed cytogenetic analysis to determine whether down-regulation of HLTF expression in human colon cancer cells induced chromosomal abnormalities." (PMID 22452792, 2012). "The requirement of HLTF for repair of damaged DNA may also implicate a tumor suppression role in human colon cancers, where HLTF has been identified as a common target for methylation and epigenetic gene silencing." (PMID 22452792, 2012).
colon cancers (continued). "Our findings highly suggest that epigenetic inactivation of HLTF, as found in most human colon cancers, could play an important role in the progression of colon tumors to malignant cancer." (PMID 22452792, 2012). "Taken together, our data indicate that down-regulation of HLTF in human colon cancer cells may promote tumor growth and malignancy, similar to what we found in the Hltf -/-/Apcmin/+ mouse model." (PMID 22452792, 2012). "APC and CMTM3, EXO1 and HLTF are reported to be hyper-methylated in selected colon cancer samples." (PMID 22051105, 2011). "Our results strongly suggest that aberrant methylation of HLTF, which leads to the loss of this gene's function as found in most human colon cancers, could have a pathogenetic role rather than being a consequence of colorectal carcinogenesis." (PMID 22452792, 2012). "Therefore, the loss of HLTF function is unlikely to mis-regulate the expression of specific genes, leading to the development of colon cancers." (PMID 22452792, 2012). "Besides colon tumors, HLTF methylation was also commonly detected in human gastric tumors or cancers, but not in other human cancers, such as lung and breast cancers, suggesting that this epigenetic alteration is unique to the tumors of the gastrointestinal tract." (PMID 22452792, 2012). "However, although HLTF methylation has been demonstrated as a common event in human colon cancer and it has been suggested as a prognostic biomarker, it is largely unclear whether this epigenetic event is important for the development of this cancer." (PMID 22452792, 2012). "Given the high frequency of epigenetic inactivation by hypermethylation of HLTF in human colon cancers, our studies strongly suggest that this epigenetic alteration could be directly involved in the development of colon cancer rather than a consequence of this carcinogenesis." (PMID 22452792, 2012).
adenoma (4 papers, 2012 to 2021). A neoplasm arising from the epithelium. "The helicase-like transcription factor (HLTF) tumor suppressor gene is hypermethylated during the transition from aberrant crypt focus to adenoma/polyp." (PMID 31461471, 2019). "HLTF immunohistochemical expression was investigated in biopsies of adenomas and papillary carcinomas using two different anti-HLTF antibodies." (PMID 25005870, 2014). "In colloid nodules and adenomas, HLTF is localized in both the nucleus and the cytoplasm of follicular cells, but with a significantly higher staining intensity at the nuclear level." (PMID 25005870, 2014). "In adenomas, HLTF was localized in both the nucleus and the cytoplasm of cells but with significantly higher staining intensity at the nuclear level." (PMID 25005870, 2014). "Using the ART2 antibody, HLTF was detected in both the nucleus and the cytoplasm of follicular cells in adenomas." (PMID 25005870, 2014). "By contrast, with the anti-COOH antibody, HLTF staining was abolished both in adenomas and papillary carcinomas, demonstrating the expression of truncated forms that lack DNA repair ability." (PMID 25005870, 2014). "Adenomas presented very pronounced nuclear HLTF immunostaining, whereas papillary carcinomas exhibited HLTF only in the cytoplasm." (PMID 25005870, 2014). "The number of HLTF positive nuclei was clearly higher in the adenomas group (30%) than in the papillary carcinomas group (5%)." (PMID 25005870, 2014). "In adenomas, the HLTF staining was moderate in the cytoplasm, but a pronounced nuclear staining was clearly observed." (PMID 25005870, 2014). "The frequency of HLTF promoter methylation was found to increase drastically between early stage of adenomas and advanced adenomas, suggesting that this epigenetic alteration could be a later event in colon carcinogenesis." (PMID 22452792, 2012).
gastric cancer (4 papers, 2006 to 2023). A primary or metastatic malignant neoplasm involving the stomach. "HLTF methylation plays a role in the early stages of gastric carcinogenesis in patients with family histories and may be a valuable susceptible marker for the risk of gastric cancer in individuals with family predisposition." (PMID 28418867, 2017). "Similarly, the HLTF gene was methylated and epigenetically silenced in 30–70% of human colon and gastric cancers, suggesting a role in tumor suppression." (PMID 16762066, 2006). "In fact, in the very study where HLTF was initially found to be inactivated in a number of colon and gastric cancers, neither HLTF promoter hypermethylation nor loss of expression was found in cancers of other organs such as the breast and the lung." (PMID 16762066, 2006).
HCMV infection (4 papers, 2018 to 2021). "In order to demonstrate antiviral restriction by HLTF, shRNA-mediated knockdown was performed revealing enhanced HCMV infection in HLTF-depleted cells under conditions of low multiplicity of infection." (PMID 33530304, 2021). "HLTF thus acts to restrict significantly the efficiency with which a low MOI HCMV infection activates immediate-early gene expression, with an efficiency similar to that of the recognized HCMV restriction factor Sp100." (PMID 30122656, 2018). "During HCMV infection, HLTF transcripts increase while HLTF protein levels decline." (PMID 30986950, 2019). "Furthermore, pUL145 co-precipitates components of the CRL complex comprising Cul4A, DDB1, and DDA1, indicating that pUL145 assembles a functional CRL complex to degrade the host restriction factor HLTF very early during HCMV infection." (PMID 30986950, 2019). "The enhancement of HCMV infection was confirmed using five independently derived CRISPR/Cas9 knockdown lines for both Sp100 and HLTF." (PMID 30122656, 2018). "Notably, this group contained the known HCMV restriction factors Sp100, MORC3, DAXX, and HLTF in addition to cell cycle regulating protein ANAPC1, all of which have been reported to be degraded during HCMV infection by ourselves and others." (PMID 33585265, 2020).
gastric tumors (3 papers, 2006 to 2019). "Similarly, the HLTF gene was recently found to be inactivated by hypermethylation in a number of advanced colon and gastric tumors." (PMID 16762066, 2006).
hepatocellular carcinoma (3 papers, 2020 to 2024). A malignant tumor that arises from hepatocytes. "For example, mutations and promoter methylations of the human RAD5 ortholog, Helicase-Like Transcription Factor (HLTF), are observed in hepatocellular carcinoma." (PMID 32994210, 2020). "Helicase-like transcription factor (HLTF) has been found to be involved in the progression of several tumors, but the role of HLTF in hepatocellular carcinoma (HCC) progression has not been studied." (PMID 36670110, 2023).
leukemia (3 papers, 2006 to 2026). A malignant (clonal) hematologic disorder, involving hematopoietic stem cells and characterized by the presence of primitive or atypical myeloid or lymphoid cells in the bone marrow and the blood. "The concept that HLTF might participate in the regulation of differentiation is also supported by the time course of its expression during erythrocyte differentiation, and the fact that forced HLTF overexpression results in inappropriate β-globin gene switching in a human leukemia cell line." (PMID 16762066, 2006).